ENSG00000285816 (novel protein, POLA2-CDC42EP2 readthrough)
Gene: Protein-coding gene on chromosome 11 (65,261,928 to 65,326,543, forward strand). Ensembl gene ENSG00000285816.
Genetic constraint (gnomAD): Missense variants: 414 observed, 499.94 expected, observed/expected ratio (o/e) 0.83, 90% interval 0.76 to 0.9. Synonymous variants: 189 observed, 205.26 expected, observed/expected ratio (o/e) 0.92, 90% interval 0.82 to 1.04.